CYP1A1 (cytochrome P450 family 1 subfamily A member 1)
Description:
A cytochrome P450 monooxygenase involved in the metabolism of various endogenous substrates, including fatty acids, steroid hormones and vitamins. Mechanistically, uses molecular oxygen inserting one oxygen atom into a substrate, and reducing the second into a water molecule, with two electrons provided by NADPH via cytochrome P450 reductase (NADPH--hemoprotein reductase). Catalyzes the hydroxylation of carbon-hydrogen bonds. Exhibits high catalytic activity for the formation of hydroxyestrogens from estrone (E1) and 17beta-estradiol (E2), namely 2-hydroxy E1 and E2, as well as D-ring hydroxylated E1 and E2 at the C15-alpha and C16-alpha positions. Displays different regioselectivities for polyunsaturated fatty acids (PUFA) hydroxylation. Catalyzes the epoxidation of double bonds of certain PUFA. Converts arachidonic acid toward epoxyeicosatrienoic acid (EET) regioisomers, 8,9-, 11,12-, and 14,15-EET, that function as lipid mediators in the vascular system. Displays an absolute stereoselectivity in the epoxidation of eicosapentaenoic acid (EPA) producing the 17(R),18(S) enantiomer. May play an important role in all-trans retinoic acid biosynthesis in extrahepatic tissues. Catalyzes two successive oxidative transformation of all-trans retinol to all-trans retinal and then to the active form all-trans retinoic acid. May also participate in eicosanoids metabolism by converting hydroperoxide species into oxo metabolites (lipoxygenase-like reaction, NADPH-independent).
Synonyms: CYPIA1; P450DX; P1-450; P450-C; CP11; AHH; CYP1
Tractability: Small molecule: a structure with a bound ligand is known; a high-quality ligand is known; it belongs to a druggable protein family. Antibody: UniProt places it where antibodies can reach, with medium confidence. PROTAC: ubiquitination databases record sites on it; a small molecule that binds it is known.
Target class: Enzyme; Cytochrome P450 family 1; Cytochrome P450 family 1A; Cytochrome P450 1A1; Cytochrome P450
Chemical probes: PD082131, PD083165
Safety:
Unwanted effects reported when the protein is acted on. In parentheses: how it was acted on, where the effect was seen, and who reports it.
Accumulation, Liver lipid (activation; source: AOP-Wiki)
Gene: Protein-coding gene on chromosome 15 (74,719,542 to 74,725,536, reverse strand). Ensembl gene ENSG00000140465.
Subcellular location: Endoplasmic reticulum membrane; Mitochondrion inner membrane; Microsome membrane; Cytoplasm
Pathways (Reactome):
Metabolism: Biosynthesis of protectins; PPARA activates gene expression; Synthesis of (16-20)-hydroxyeicosatetraenoic acids (HETE); Synthesis of epoxy (EET) and dihydroxyeicosatrienoic acids (DHET); Xenobiotics
Gene Ontology:
Molecular function: arachidonate monooxygenase activity; estrogen 16-alpha-hydroxylase activity; estrogen 2-hydroxylase activity; long-chain fatty acid omega-1 hydroxylase activity; long-chain fatty acid omega-hydroxylase activity; oxidoreductase activity; oxidoreductase activity, acting on paired donors, with incorporation or reduction of molecular oxygen, reduced flavin or flavoprotein as one donor, and incorporation of one atom of oxygen; protein binding; vitamin D 24-hydroxylase activity; Hsp70 protein binding; Hsp90 protein binding; monooxygenase activity; oxygen binding; steroid hydroxylase activity; arachidonate 11,12-epoxygenase activity; arachidonate 14,15-epoxygenase activity; arachidonate 8,9-epoxygenase activity; demethylase activity; enzyme binding; fatty acid omega-1 hydroxylase activity; flavonoid 3'-monooxygenase activity; heme binding; hydroperoxy icosatetraenoate dehydratase activity; iron ion binding; oxidoreductase activity, acting on diphenols and related substances as donors; and 1 more
Biological process: estrogen metabolic process; fatty acid metabolic process; lipid hydroxylation; long-chain fatty acid metabolic process; retinol metabolic process; steroid metabolic process; vitamin D metabolic process; xenobiotic metabolic process; epoxygenase P450 pathway; ethylene metabolic process; long-chain fatty acid biosynthetic process; omega-hydroxylase P450 pathway; steroid catabolic process; toxin metabolic process; xenobiotic catabolic process; 9-cis-retinoic acid biosynthetic process; camera-type eye development; cellular response to copper ion; coumarin metabolic process; dibenzo-p-dioxin catabolic process; dibenzo-p-dioxin metabolic process; digestive tract development; flavonoid metabolic process; hepatocyte differentiation; hormone metabolic process; and 25 more
Cellular component: mitochondrion; cytoplasm; endoplasmic reticulum membrane; mitochondrial inner membrane
Genetic constraint (gnomAD): Loss-of-function variants: 45 observed, 39.19 expected, observed/expected ratio (o/e) 1.15, 90% interval 0.9 to 1.47. The upper end of that interval is the gene's LOEUF score, 1.47, which puts it in group 6 of 6, group 1 being the genes least tolerant of losing a copy. Missense variants: 637 observed, 686.14 expected, observed/expected ratio (o/e) 0.93, 90% interval 0.87 to 0.99. Synonymous variants: 280 observed, 272.42 expected, observed/expected ratio (o/e) 1.03, 90% interval 0.93 to 1.13.
Homologues: Orthologues: chimpanzee CYP1A1 (99% identical), macaque CYP1A1 (94% identical), pig CYP1A1 (82% identical), mouse Cyp1a1 (80% identical), rat Cyp1a1 (79% identical), guinea pig CYP1A1 (78% identical), rabbit CYP1A1 (77% identical), dog CYP1A1 (76% identical), tropical clawed frog cyp1a1 (62% identical), zebrafish cyp1a (56% identical). Paralogues in human: CYP1A2 (72% identical), CYP1B1 (38% identical).
Diseases named in the same sentence as CYP1A1 in open-access papers:
CYP1A1 is named in the same sentence as 262 diseases in open-access papers, as found by Europe PMC text mining. Sharing a sentence is not in itself a finding about the gene and the disease. The quoted sentences say what the papers report.
breast carcinoma (128 papers, 1996 to 2026). "The polymorphism of CYP1A1 has been reported to alter susceptibility to various types of cancers, including lung, head, neck, bladder, and breast cancer." (PMID 38485870, 2024). "In the past decades, several epidemiological studies have reported the relationship of CYP1A1 gene single nucleotide polymorphism (SNP) with breast cancer, cervical cancer, and endometrial cancer." (PMID 39384367, 2024). "Increasing evidence has linked CYP1A1*2A A2455G MspI1 polymorphism with renal cell carcinoma, esophageal, lung, colorectal, and breast cancers with the prevalence of Ph+ve CML." (PMID 39769254, 2024). "CYP1A1, a key enzyme of estrogen metabolism, is also associated with breast cancer proliferation and survival." (PMID 36984849, 2023). "For European-Americans, carrying the CYP1A1*2 C genotype was associated with increased breast cancer risk (odds ratio (OR) = 1.71, 95%CI = 1.09–2.67)." (PMID 36203093, 2022). "LUCAT1 is a protein found in breast cancer cells with stem cell properties, and it has been linked to cell survival, and CYP1A1 has been associated with carcinogenesis." (PMID 34947458, 2021). "In contrast, negligible relations between CYP1A1 6235T > C variant and gastric cancer, colorectal cancer, breast cancer and esophageal cancer risks were found." (PMID 34830558, 2021). "For instance, CYP1A1 polymorphisms are known to be associated with susceptibility to a wide variety of cancers including lung, bladder, pancreatic, and breast cancers." (PMID 30765615, 2019). "CYP1A1 gene polymorphisms and tobacco smoking are among several risk factors for various types of cancers, but their influence on breast cancer remains controversial." (PMID 29707532, 2018). "The role of CYP1A1 polymorphisms in breast cancer risk in individuals, however, has been conflicting." (PMID 29707532, 2018). "The correlation between active tobacco smoking and breast cancer showed an increased risk among women with certain CYP1A1 mutant genotypes." (PMID 29707532, 2018). "The interaction between several compounds in tobacco smoke such as polycyclic hydrocarbons and CYP1A1 genotypes has been reported to influence risk of breast cancer." (PMID 29707532, 2018). "The risk of breast cancer related CYP1A1 m1 and m2 polymorphisms were ascertained between smoking and non-smoking patients." (PMID 29707532, 2018). "Conversely, CYP1A1 gene polymorphisms were associated with a lower risk of breast cancer among Japanese women." (PMID 29707532, 2018). "Some studies have shown that CYP1A1 polymorphisms are significantly associated with breast cancer risk consistent with this study." (PMID 29707532, 2018). "We analyzed the possible association of CYP1A1 gene polymorphisms and tobacco smoking-related breast cancer in women from Iraq." (PMID 29707532, 2018). "Association of smoking risk with CYP1A1 m1 and CYP1A1m2 genotype distribution among women with breast cancer (patients only)." (PMID 29707532, 2018). "There are also reports of significant interactions with smoking and polymorphisms in carcinogen metabolism genes NAT2 and CYP1A1 as well as breast cancer susceptibility single-nucleotide polymorphisms." (PMID 29162146, 2017). "E2 and its hydroxylated metabolites resulting from CYP1B1 and CYP1A1 have been implicated in breast cancer." (PMID 28212313, 2017). "In parallel with this finding, epidemiological studies showed an inverse association between a higher intake of flavonoids and breast cancer risk which was attributed to selective inhibition of flavonoids to CYP1A1 expression." (PMID 27800121, 2016). "When smokers were stratified by smoking duration, we only observed differences in long-term smokers, and the CYP1A1 Ile462Ile genotype was associated with increased risk of breast cancer (OR = 7.12 (1.98–25.59))." (PMID 27754415, 2016).
breast carcinoma (continued). "Certain genotypes of several genetic polymorphisms in enzymes involved in the metabolism of xenobiotics (such as CYP1A1) or in DNA repair genes have been suggested to alter the risk of breast cancer." (PMID 27754415, 2016). "We examined the influence of CYP1A1 A4889G and T6235C polymorphisms on the risk of sporadic breast cancer." (PMID 26598080, 2015). "Women with the CYP1A1 4889AG+GG genotype and earlier first full-term pregnancies had a 1.87-fold (95% CI: 1.32–2.67) increased risk of sporadic breast cancer compared to the other study participants." (PMID 26598080, 2015). "The present study evaluates the existence of CYP1A1 polymorphism in a number of breast cancer samples." (PMID 24847427, 2014). "Regarding these findings, the important issues are examining relationship between CYP1A1 polymorphism and breast cancer risk considering environmental factor (especially dietary factor) that has not been evaluated in our study." (PMID 24847427, 2014). "A number of epidemiological studies have shown that genetic variants of human CYP1A1 gene are significantly associated with the susceptibilities to lung and breast cancers." (PMID 24287985, 2013). "Unconditional multivariable logistic regression analysis of association between breast cancer risk, fungicide exposure and CYP1A1*2A allele, PEI, 1999–2003." (PMID 22754477, 2012). "In a population-based case-control study, we evaluated breast cancer risk in relation to PCBs and the CYP1A1 polymorphisms M1 (also known as CYP1A1*2A), M2 (CYP1A1*2C), M3 (CYP1A1*3), and M4 (CYP1A1*4)." (PMID 15642161, 2005). "Two recent epidemiologic studies showed an increased risk of breast cancer among postmenopausal white women with at least one M2 (valine) variant allele of CYP1A1 and a high serum level of PCBs." (PMID 15642161, 2005). "On the basis of this model, individuals with higher CYP1A1 activity would be at increased risk of breast cancer when exposed to high levels of PCBs." (PMID 15642161, 2005). "We estimated the joint effects of plasma levels of total PCBs and CYP1A1 genotypes in association with breast cancer, using previously collected data from a population-based case-control study of African American and white women in North Carolina." (PMID 15642161, 2005). "We used data from the Carolina Breast Cancer Study (CBCS), a population-based case-control study of African American and white women in North Carolina, to evaluate the effects of PCBs and CYP1A1 genotypes in relation to breast cancer risk." (PMID 15642161, 2005). "We conclude that CYP1A1 polymorphism is a susceptibility factor for breast cancer in postmenopausal Chinese women in Taiwan." (PMID 10468307, 1999). "Thus, protective effect of CYP1B1-polymorphisms with doxorubicin and paclitaxel basedchemotherapy induced N-HEM toxicity and CYP2C9- polymorphisms with paclitaxel induced body ache and CYP1A1-polymorphisms with peripheralneuropathy in breast cancer patients." (PMID 40092865, 2024). "However, carrying the CYP1A1*2 C allele in combination with a SULT1A1*2 allele was strongly protective against developing breast cancer (OR = 0.14, 95%CI = 0.04–0.56) compared with women carrying only the CYP1A1*2 C allele." (PMID 36203093, 2022). "In addition to lung cancer, colorectal cancer, breast cancer, leukemia, esophageal carcinoma and prostate cancer, CYP1A1 polymorphisms can also lead to other diseases such as ulcerative colitis, colorectal adenoma, myocardial infarction, etc.." (PMID 32882964, 2020). "This interaction may highlight the significant influence of the CYP1A1 gene polymorphisms on various risk factors, such as tobacco smoking, associated with breast cancer." (PMID 29707532, 2018). "In this case–control study, gene polymorphism of CYP1A1 gene (CYP1A1m1, T6235C and CYP1A1m2, A4889G) of 199 histologically verified breast cancer patients’ and 160 cancer-free control women’s specimens were performed by using PCR-based restriction fragment length polymorphism." (PMID 29707532, 2018).
breast carcinoma (continued). "Newer evidence found that the complex interaction of high serum levels of PCBs and a particular variant (exon 7) of the CYP1A1 gene was associated with an increased risk for breast cancer (HR = 2.78; 95% CI = 0.99–7.82, compared to women with lower PCB levels and the wild-type genotype)." (PMID 28865460, 2017). "Besides the study on the Indianpopulation, other studies have shown that beinghomozygous for the CYP1A1*2A variant increasedsusceptibility to estrogen-related breast cancer inAfrican-Americans." (PMID 28868835, 2017). "The CYP1A1 A4889G and T6235C polymorphisms may alter the risk of sporadic breast cancer in Brazilian women." (PMID 26598080, 2015). "Furthermore, reduced CYP1A1 enzymatic activity has been linked to constitutive activation of the AhR and resistance of breast cancer cells to apoptosis induced by DMBA." (PMID 26715507, 2015). "CYP1A1 Ile462Val polymorphism might have a correlation with increased risks of lung cancer, cervical cancer, colorectal cancer, esophageal cancer and breast cancers." (PMID 23056546, 2012). "Our results confirm findings from previous studies with respect to the highly inducible CYP1A1 M2 genotype, and suggest that M3-containing genotypes might also modify risk of breast cancer associated with PCB exposure in African American women." (PMID 15642161, 2005). "Furthermore, we sought to determine whether CYP1A1 knockdown inhibits AKT phosphorylation since a recent study showed that CYP1A1 is associated with the PI3K-AKT signaling pathway in breast cancer cell lines." (PMID 27203547, 2016). "Since cytochrome P4501A1 (CYP1A1) is involved in the metabolism of environmental carcinogens or oestrogen, we hypothesized that CYP1A1 genetic polymorphism may be a susceptibility factor for breast cancer." (PMID 10468307, 1999). "Tangeretin was subsequently shown to induce CYP1 activity and CYP1A1/CYP1B1 expression in MCF7 and MDA-MB-468 cells, suggesting that this flavone inhibits the proliferation of breast cancer cells via CYP1A1/CYP1B1-mediated metabolism to 4′-hydroxy tangeretin." (PMID 40807256, 2025). "In this context, the detoxifying enzyme named cytochrome P450 1A1 (CYP1A1) has been confirmed as overexpressed in several cancers such as lung, digestive tract, and breast cancers." (PMID 40006600, 2025). "The study also revealed the inhibition of CYP1A1 with carnosol-induced cell death (apoptosis) in breast cancer cells, confirming the synergistic effect of cisplatin and carnosol." (PMID 38495994, 2024). "CYP1A1 induction has been observed in response to various stimuli such as benzo[a]pyrene (in T-47D human breast cancer cells), sodium arsenide (in rats), and cadmium/chromium." (PMID 38892012, 2024). "Several studies focused on the relationship between CYP1A1 gene and several other cancer types, including oral cancer, lung cancer, larynx cancer, breast cancer, cervical cancer and endometrial cancer risk in different populations." (PMID 39384367, 2024). "Fluorescence probe 5 was designed for the identification of CYP1A1, contributing to the diagnosis and treatment of breast cancer." (PMID 38495994, 2024). "Using RT-PCR, CYP1A1 was measured in mammary carcinoma cells that were treated prior with 1 μM of DMBA in both the absence and presence of curcumin and after 24 h, a 15-fold increase in CYP1A1 mRNA was observed." (PMID 38518996, 2024). "AHR activity was determined using the EROD activity assay, a standard method for evaluating the receptor’s canonical pathway by measuring CYP1A1 induction in MCF-7 human breast cancer cells." (PMID 39204085, 2024). "Subsequently, we demonstrated for the first time that THC regulated TIME to inhibit breast cancer proliferation and metastasis through the CYP1A1/NF-κB signaling pathway in vitro and in vivo." (PMID 36707875, 2023). "After CYP1A1 knockdown, group, and the inhibitory effect of THC on the proliferation of breast cancer cells was enhanced after CYP1A1 knockdown." (PMID 36707875, 2023).